FNDC1 (fibronectin type III domain containing 1)
Description:
May be an activator of G protein signaling.
Synonyms: FNDC2; KIAA1866; MEL4B3; bA243O10.1; dJ322A24.1; AGS8
Tractability: Antibody: UniProt places it where antibodies can reach, with high confidence; UniProt predicts a signal peptide or a membrane-spanning region; its Gene Ontology location is reachable by antibodies, with medium confidence.
Gene: Protein-coding gene on chromosome 6 (159,169,353 to 159,272,112, forward strand). Ensembl gene ENSG00000164694.
Subcellular location: Secreted
Subcellular location (Human Protein Atlas): Nuclear speckles; Predicted to be secreted
Gene Ontology:
Cellular component: non-collagenous component of interstitial matrix; extracellular region
Genetic constraint (gnomAD): Loss-of-function variants: 75 observed, 134.35 expected, observed/expected ratio (o/e) 0.56, 90% interval 0.46 to 0.68. The upper end of that interval is the gene's LOEUF score, 0.68, which puts it in group 2 of 6, group 1 being the genes least tolerant of losing a copy. Missense variants: 2,418 observed, 2,344.7 expected, observed/expected ratio (o/e) 1.03, 90% interval 1 to 1.07. Synonymous variants: 1,037 observed, 964.66 expected, observed/expected ratio (o/e) 1.08, 90% interval 1.02 to 1.13.
Homologues: Orthologues: chimpanzee FNDC1 (98% identical), macaque FNDC1 (95% identical), dog FNDC1 (77% identical), pig FNDC1 (75% identical), rat Fndc1 (70% identical), mouse Fndc1 (69% identical), guinea pig FNDC1 (67% identical), rabbit FNDC1 (64% identical), tropical clawed frog fndc1 (37% identical), zebrafish fndc1 (32% identical). Paralogues in human: ABI3BP (18% identical).